LINC01820 (long independently transcribed non-coding RNA 1820)
Gene: Long non-coding RNA gene on chromosome 2 (46,347,186 to 46,429,238, reverse strand). Ensembl gene ENSG00000228100.
Diseases named in the same sentence as LINC01820 in open-access papers:
LINC01820 is named in the same sentence as 1 disease in open-access papers, as found by Europe PMC text mining. Sharing a sentence is not in itself a finding about the gene and the disease. The quoted sentences say what the papers report.
tumor (1 paper, 2021). "As LINC01820 and LINC02257 did not regulate tumor behavior by lncRNA-miRNA-mRNA manner, RNA-binding proteins which connected with the two hub m6A-lncRNAs were investigated." (PMID 34295922, 2021).